MYCN (MYCN proto-oncogene, bHLH transcription factor)
Diseases named in the same sentence as MYCN in open-access papers (continued):
Sharing a sentence is not in itself a finding about the gene and the disease.
metastatic disease (58 papers, 2009 to 2025). "20%–25% of all NB at diagnosis harbour MYCN amplification and this percentage rises in high‐risk and metastatic tumours." (PMID 41420301, 2025). "MYCN amplification is the primary oncogenic driver associated with metastatic disease and dismal survival in high-risk NB1." (PMID 41279557, 2025). "Glycolytic gene expression is increased in MYCN amplified, metastatic tumours and is associated with worse event free survival." (PMID 41420301, 2025). "Other critical genetic changes include 1p loss of heterozygosity, commonly associated with unresectable metastatic disease and MYCN amplification, and 11q deletion, which correlates with advanced disease stages and poor survival." (PMID 40104501, 2025). "Amplification of MYCN indicates aggressive or high-risk metastatic disease and poor patient prognosis." (PMID 37274289, 2023). "Established clinico-molecular risk-features (age at diagnosis, metastatic disease, histological variants, extent of surgical resection and amplification of MYCN) were equivalently distributed between both groups (online resource)." (PMID 37014508, 2023). "Among patients with MYCN amplification, 11q deletion, unfavorable histology and metastatic disease, those who additionally had 1p deletion were associated with significantly worse OS (P = 0.046, 0.032, and 0.011, respectively)." (PMID 35768791, 2022). "Comparing the 205 patients with evaluable 1p status, cases with 1p deletion were associated with established prognostic factors MYCN amplification, metastatic disease and COG high risk status (P < 0.001, P = 0.065, and P = 0.012, respectively)." (PMID 35768791, 2022). "Based on single-cell-based sequencing data from the GEMs, we observed that the overexpression of MYCN in combination with the loss of Rb1 resulted in the rapid formation of aggressive, metastatic tumors with neuroendocrine-like features." (PMID 34099734, 2021). "Patients with HRNB frequently present with widely metastatic disease, with tumors harboring recurrent genetic aberrations (MYCN amplification, TERT rearrangements, and ATRX mutations), which are mutually exclusive and capable of promoting TMM." (PMID 34439779, 2021). "We observed a case of NB showing high-grade amplification of six loci besides MYCN in a 28-month-old girl with high-risk metastatic disease." (PMID 34830942, 2021). "This is consistent with the large number of patients having high-risk non-MYCN-amplified tumours that present with metastatic disease." (PMID 33578855, 2021). "A recent study by this group revealed that metastatic tumors had higher infiltration of tumor associated macrophages (TAMs), as compared to loco-regional tumors in non-MYCN amplified NB tumors." (PMID 32722460, 2020). "In this same position, three SNPs, namely CASC15, CASC15-S, and CASC14, were identified by Genome-Wide Association Study (GWAS) and associated with metastatic disease, amplification of MYCN oncogene, and more advanced disease." (PMID 30791380, 2019). "Amplification in tumor cells of MYCN, the major oncogenic driver, patients’ age over 18 months, and the presence at diagnosis of a metastatic disease (stage IV, M) identify NB at high risk of treatment failure." (PMID 24575100, 2014). "Our findings suggest that dual targeting of eIF4F-mediated translation initiation and XPO1-mediated nuclear export has potential to combat high-risk NB, particularly in patients with MYCN-amplified metastatic tumors, who currently have limited treatment options." (PMID 41279557, 2025). "However, 50% of patients are classified as having high-risk disease due to older age (>18 months) and metastatic disease or having locally advanced tumors with MYCN amplifications." (PMID 39479120, 2024). "Other statistically significant clinical correlations with lower NET protein expression (patients with high-risk disease and patients with metastatic disease) may be driven by this association with MYCN amplification." (PMID 23050139, 2012).
metastatic disease (continued). "Patients with metastatic disease and MYCN amplification who received standard chemotherapy, surgery, local radiotherapy, and autologous stem cell transplantation were randomized to receive isotretinoin alone or in combination with dinutuximab." (PMID 40606987, 2025). "Presenting features of NB-SCI patients differed from other NBs for older median age, prevalence of thoracic vs. abdominal primary site, prevalence of localized vs. metastatic disease and lower incidence of MYCN gene amplification." (PMID 36299690, 2022). "Approximately 45% of Nb cases are considered highrisk (HR), especially those over 18 months with metastatic disease beyond regional nodes and patients with MYCN gene amplification." (PMID 33480449, 2021). "Expression of the most significant TrkA-correlated miRNA, miR-542-5p, also discriminated between local and metastatic disease, and was inversely correlated with MYCN amplification and EFS." (PMID 33404859, 2021). "Overall, we found significantly higher gene promoter methylation rates in patients with the following characteristics: metastatic tumors (either stage M or MS), aged 18 months or older at first diagnosis and MYCN amplification." (PMID 25767620, 2015). "High promoter methylation rates of these genes were found in patients with metastatic tumors (either stage metastatic (M) or metastatic special (MS)), 18 months or older at first diagnosis, MYCN amplification, relapsed, and dead." (PMID 25767620, 2015). "All metastatic tumors with amplified MYCN genes are aggressive, whereas metastatic tumors with non amplified MYCN genes have variable clinical behaviors influenced by the patient's age at diagnosis." (PMID 20624283, 2010). "However, MYCN-amplified NB cells frequently develop metastatic tumors at the distant organs, which are inaccessible for intratumor injections of oncolytic adenoviruses." (PMID 32637577, 2020). "Fifty-two (96.3%) patients had metastatic tumors and 25 (48.1%) patients had MYCN-amplified tumors." (PMID 28511709, 2017). "Patients with MYCN positive metastatic disease may have an adverse outcome and represent a great challenge for oncologists in this field." (PMID 24396620, 2013). "However, our capacity to noninvasively identify patients at higher risk for developing metastatic disease or those with MYCN-amplified tumors who are not candidates for eye salvage is still limited." (PMID 35433448, 2022). "Similarly, another study showed that aberrant methylation of the PCDHB family members is associated with other clinical factors that indicate poor clinical outcome, such as MYCN amplification, metastatic tumor stage, and older age of the patient at the time of diagnosis." (PMID 33404859, 2021). "Interestingly, the stratified analysis found a very poor survival in association with high expression values of TSSC1 gene among patients with clinical characteristics similar to those of our patient, i.e., metastatic disease, age > 18 months, and MYCN amplified." (PMID 34830942, 2021). "A clonal driver mutation in MYCN (MIM: 164840; CRC-190), and subclonal driver mutations in ELF4 (MIM: 300775; 083-03), PTPRB (MIM: 176882; CRC-233 lymph node metastasis), FUS (MIM: 137070), and ERCC4 (MIM: 133520) in CRC-449 were all specific to metastatic tumours." (PMID 33053768, 2020). "However, German protocols include MYCN amplified resectable tumours on their high-risk protocols but exclude metastatic disease without MYCN amplification diagnosed between 12 and 18 months." (PMID 30822684, 2019).
metastatic disease (continued). "However, the decision to treat patients on national high-risk protocols varies, e.g. in most of Europe, HRNB is defined as patients over 12 months with metastatic disease, MYCN amplified localised unresectable disease and infants with MYCN amplified metastatic disease." (PMID 30822684, 2019). "NB53 did not receive neoadjuvant therapy and the primary tumor (NB53-T1) presented an Sa+1pL genomic profile (MYCN amplification and 1p loss but no 17q gain nor 11q loss), while the liver metastatic tumor obtained 14 months after therapy (NB53-T2) exhibited a P1a pattern." (PMID 28915622, 2017). "The overexpression of the MYCN and NCYM proteins in primary and metastatic tumor cells was confirmed by immunohistochemistry." (PMID 24391509, 2014). "In a study focused on Nb with nonamplified MYCN (MYCN‐NA), M2 TAMs were more abundant in HR patients, those > 18 months with metastatic disease." (PMID 33480449, 2021). "SIOPEN 99.2 enrolled infants with MYCN nonamplified, metastatic disease that did not have metastases to the bone, central nervous system, lung, or pleura to evaluate the ability to only give chemotherapy for symptomatic patients." (PMID 30754710, 2019). "This cohort reflected the differences between localized and metastatic NB; in fact, children with localized NB were younger than those with metastatic disease, and they did not present MYCN amplification in the primary tumors, and were all alive at follow-up." (PMID 29721180, 2018). "A number of studies have shown that in patients less than 18 months of age with metastatic disease, hyperdiploidy in combination with a non-amplified MYCN gene, and a lack of specific SCAs (such as 11q deletion) is commonly predictive of a favorable outcome." (PMID 25161957, 2014). "Moreover, despite a high MYCN expression, which in humans correlates with metastatic disease, no overt metastases are seen in the TH-MYCN model." (PMID 37444423, 2023). "However, the other half of the patients constitutes a high-risk group and these patients either harbor tumors with MYCN amplification, or are older than 18 months and display metastatic disease regardless of MYCN amplification." (PMID 32722460, 2020). "However, for a subgroup of patients with diploid, MYCN nonamplified tumors and distant metastatic disease, the INRG task force recommended an age cutoff of 12 months (365 days) for the INRG classification system." (PMID 30754710, 2019). "Also included are patients with metastatic disease, <18 months of age at diagnosis with MYCN non-amplified tumors and those with stage MS disease, MYCN non-amplified tumors except patients with an unfavorable biologic feature (11 q aberration)." (PMID 30626019, 2019). "All metastatic tumours with MYCN amplification (MNA) are aggressive and considered being high-risk tumours, whereas children with metastatic disease without MNA (approximately 65%) have variable clinical behaviours depending on age at diagnosis, histopathology, and other genetic factors." (PMID 23835063, 2013). "A number of studies have shown that in patients <18 months of age with metastatic disease, hyperdiploidy in combination with a non-amplified MYCN gene and the lack of specific segmental chromosome aberrations (such as 11q deletion) are predictive of a favourable outcome." (PMID 19401703, 2009). "However, in patients <18 months of age with metastatic disease with diploid, MYCN non-amplified tumours have a statistically significantly worse outcome." (PMID 19401703, 2009). "Sex, age below 10 years, post-surgical residual disease, histological subtype, MYC and MYCN amplification, CSI dose reduction, omission of boosts, intensification with myeloablative courses, and presence or absence of metastatic disease did not impact prognosis." (PMID 39331528, 2025).
glioblastoma (57 papers, 2009 to 2025). The most malignant astrocytic tumor (WHO grade IV). "MYCN overexpression and amplification are frequently associated with glioblastoma multiforme and are documented in approximately 40% of tumor samples." (PMID 39802403, 2025). "MYCNOS, as an antisense RNA of coding gene MYCN, can play a role in the regulation of malignant tumors such as ovarian cancer 46, nephroblastoma 47, glioblastoma 48 and liver cancer 49 by regulating MYCN or other encoding genes." (PMID 37859811, 2023). "Further molecular testing illustrated features more consistent with glioblastoma: multiple large chromosomal aberrations including loss of whole chromosome 1 and 2q; gain/amplification of MYCN, MET, and CDK4; loss of CDKN2A/B; and an ATRX mutation." (PMID 30738431, 2019). "Of recent discovery, forced overexpression of MYCN has been shown to cause glioblastoma in the developing mouse forebrain, providing evidence for a tumor-initiating event that may drive pediatric glioblastoma formation during neurological development." (PMID 28401060, 2017). "Targeting MYCN with inhibitors that block the Aurora-A/MYCN complex or BET domain showed anticancer effects against glioblastoma multiforme in cell-based assays." (PMID 39802403, 2025). "In paediatric glioblastoma, H3F3A G34 mutations elevate MYCN expression via H3K36me3-dependent mechanisms, driving incurable cerebral hemispheric GBMs through MYCN overexpression in neural stem cell compartments." (PMID 40987316, 2025). "By conducting CRISPR-Cas9–mediated genome editing of SE regions, we revealed that certain H4K5acK8ac-preferred SEs were responsible for the expression of associated genes (i.e., MYCN and NFIC) in GSCs and the maintenance of glioblastoma stem-like properties." (PMID 37759202, 2023). "MiR-34a in hBMSC-derived exosomes inhibits glioblastoma cell proliferation, migration, invasion and tumorigenesis in vitro and in vivo and promotes chemosensitivity to temozolomide by suppressing MYCN." (PMID 37248542, 2023). "As AURKA inhibitors have demonstrated anti-tumor activities either as a single agent or in combination in MYCN-positive human glioblastoma and AURKs are attractive therapeutic targets in c-Myc-driven lymphoproliferative disorders." (PMID 34359608, 2021). "Astrocytoma models comprised pleomorphic xanthroastrocytomas (PXA; n = 2), MYCN subtype (n = 2), glioblastomas (IDH-wild-type; n = 5), histone H3-wild-type diffuse intrinsic pontine glioma (DIPG; n = 2), and a histone H3-wild-type astrocytic tumor (n = 1)." (PMID 31693904, 2019). "We show that MYC or MYCN amplification in patient-derived glioblastoma stem-like cells (GSCs) generates sensitivity to PARPi via Myc-mediated transcriptional repression of CDK18, while most tumors without amplification are not sensitive." (PMID 31266951, 2019). "Recently, oncogenic myc as well as mycN was reported to induce a pseudohypoxic glycolysis of glioblastoma cells, which in turn should be less dependent on neoangiogenesis." (PMID 29282022, 2017). "MYCN is amplified as low-level gain or higher in 8% of the glioblastoma samples and is connected to 21 modules." (PMID 25679508, 2015). "For example, MYCN is a target gene of ASCL1 in glioblastoma." (PMID 40498845, 2025). "In agreement with prior work, MYCN expression was highest in low-grade glioma and glioblastoma." (PMID 38748789, 2024). "To investigate whether MYCN or NFIC are involved in the maintenance of glioblastoma stem-like properties as predicted, we assessed the effects of their siRNA knockdown on 0316-GSC cells." (PMID 37759202, 2023).
glioblastoma (continued). "Cancer cells are addicted to transcription driven by SEs and thus highly dependent on CDK7 activity, as exemplified by the identification of a so-called “Achilles cluster” of genes in MYCN amplified glioblastoma, triple-negative breast cancer, and pancreatic cancer." (PMID 37385987, 2023). "Although all H3F3AK27M and EZHIP cases clustered with other diffuse midline glioma K27M tumors, the HIST2H3CK27M case (ICR-B184) was most similar to ICR-B118 and other MYCN-amplified glioblastoma in the t-statistic–based stochastic neighbor embedding projection of the methylation array data." (PMID 34737188, 2022). "AURKA inhibitor synergizes with BET inhibitor against MYCN-positive human glioblastoma." (PMID 34359608, 2021). "Likewise, we demonstrate striking enrichment of miR-17-92 members with the MYCN-3’UTR also in MYCN-driven glioblastoma KNS42 cells." (PMID 34026620, 2021). "The latest WHO classification for CNS tumors which will be released in spring 2021 still recognizes glioblastomas with primitive neuronal component, and loss of GFAP expression, MYC/MYCN gene amplification, elevated Ki67 proliferation index and increased cerebrospinal fluid dissemination." (PMID 33876327, 2021). "Also, c-MYC and MYCN amplification is a predictive biomarker for PARP inhibitor sensitivity in glioblastoma." (PMID 33134168, 2020). "For example, in a study of glioblastoma cells, several oncogenes were found on ecDNA, including MYC, MYCN, EGFR, PDGFRA, MET, the MECOM–PIK3CA–SOX2 gene cluster, and the CDK4–MDM2 gene cluster." (PMID 37448518, 2023). "Similar data have been documented in glioblastoma and lung adenocarcinoma models, where antiproliferative effects and transcriptional changes by BET inhibition occur at unchanged MYC/MYCN levels." (PMID 33668642, 2021). "Of these, MYCN amplification has been previously reported and shown to correlate with shorter survival in IDH-mutant glioblastoma, and may have contributed to the aggressive course of this case, as well." (PMID 33853673, 2021). "For comparison, the MYCN-negative NBL Neuro-2a, the glioblastoma GL261 and the fibrosarcoma 3T3 cell lines were used." (PMID 27471639, 2016).